ULBP3 (UL16 binding protein 3)
Description:
Binds and activates the KLRK1/NKG2D receptor, mediating natural killer cell cytotoxicity.
Synonyms: N2DL-3; NKG2DL3; RAET1N
Tractability: Antibody: its Gene Ontology location is reachable by antibodies, with high confidence; UniProt places it where antibodies can reach, with medium confidence; UniProt predicts a signal peptide or a membrane-spanning region.
Gene: Protein-coding gene on chromosome 6 (150,061,053 to 150,069,191, reverse strand). Ensembl gene ENSG00000131019.
Subcellular location: Cell membrane
Subcellular location (Human Protein Atlas): Vesicles; Golgi apparatus
Pathways (Reactome):
Immune System: Immunoregulatory interactions between a Lymphoid and a non-Lymphoid cell
Gene Ontology:
Molecular function: natural killer cell lectin-like receptor binding; protein binding; receptor ligand activity
Biological process: natural killer cell activation; natural killer cell mediated cytotoxicity; antigen processing and presentation of endogenous peptide antigen via MHC class I via ER pathway, TAP-independent; antigen processing and presentation of endogenous peptide antigen via MHC class Ib; positive regulation of T cell mediated cytotoxicity; signal transduction
Cellular component: plasma membrane; external side of plasma membrane
Genetic constraint (gnomAD): Loss-of-function variants: 23 observed, 24.83 expected, observed/expected ratio (o/e) 0.93, 90% interval 0.67 to 1.31. The upper end of that interval is the gene's LOEUF score, 1.31, which puts it in group 5 of 6, group 1 being the genes least tolerant of losing a copy. Missense variants: 305 observed, 322.11 expected, observed/expected ratio (o/e) 0.95, 90% interval 0.86 to 1.04. Synonymous variants: 114 observed, 122.37 expected, observed/expected ratio (o/e) 0.93, 90% interval 0.8 to 1.09.
Homologues: Orthologues: chimpanzee ULBP3 (96% identical), macaque ULBP3 (82% identical), pig ULBP1 (41% identical), mouse Ulbp1 (23% identical), tropical clawed frog mhc1-uea (15% identical), zebrafish mhc1lda (15% identical), zebrafish si:dkey-52p2.5 (14% identical), zebrafish mhc1lga (13% identical), zebrafish mhc1lja (13% identical), zebrafish mhc1lfa (13% identical), zebrafish mhc1laa (12% identical), zebrafish mhc1lla (12% identical), and 2 more. Paralogues in human: RAET1G (54% identical), ULBP1 (54% identical), ULBP2 (54% identical), RAET1L (53% identical), RAET1E (37% identical), HLA-E (26% identical), HLA-F (25% identical), HLA-C (25% identical), HLA-A (24% identical), HLA-B (24% identical), HLA-G (23% identical), MR1 (22% identical), and 10 more.
Diseases named in the same sentence as ULBP3 in open-access papers:
ULBP3 is named in the same sentence as 47 diseases in open-access papers, as found by Europe PMC text mining. Sharing a sentence is not in itself a finding about the gene and the disease. The quoted sentences say what the papers report.
glioma (9 papers, 2015 to 2023). A benign or malignant brain and spinal cord tumor that arises from glial cells (astrocytes, oligodendrocytes, ependymal cells). "As a result, the level of promoter methylation for Micb, Ulbp1 and Ulbp3 is higher in gliomas with mutated IDH than with wild type IDH, and the two primary transcriptionally silenced NKG2D ligands ULBP1 and ULBP3 were responsive to DNMTi." (PMID 34681626, 2021). "One study showed that gliomas with IDH1 and IDH2 mutation downregulate expression of NKG2D ligands (ULBP1 and ULBP3) by affecting DNA methylation, thus escaping NKs immune surveillance." (PMID 37928272, 2023). "It was found to restore ULBP1 and ULBP3 expression in IDH mutant glioma cells." (PMID 37274252, 2023). "Furthermore, decitabine-mediated hypomethylation restores ULBP1 and ULBP3 expression in IDH-mut glioma cells, suggesting a potential method to sensitize IDH-mut gliomas to NK cell-mediated immune surveillance in the clinic." (PMID 35267433, 2022). "First, we monitored by flow cytometry the cell surface expression of the NKG2D ligand MICA, MICB, ULBP1, ULBP2, ULBP3, ULBP4 and MHC class I on untreated and SR141716-treated U251 glioma cells at 24 h to exclude that the possibility of observed effects are linked to the stress of dying cells." (PMID 26008966, 2015). "On the other hand, studies on glioma and nasopharyngeal carcinoma have documented contrasting results, showing that upregulation of the cytokines TGF-β/IFN-γ and increased PD-L1 expression can lead to selective downregulation of ULBP3 and 4 to facilitate tumor escape." (PMID 37256148, 2023).
breast carcinoma (4 papers, 2020 to 2025). "The breast cancer cell line MB543 did not express ULBP1, but ULBP3 was partially expressed." (PMID 35965586, 2022).
chronic lymphocytic leukemia (4 papers, 2018 to 2026). "These cells recognize ULBP3 which is expressed on chronic lymphocytic leukemia of B-cell type (B-CLL) through NKR." (PMID 33664732, 2020). "In independent studies, other NKG2D ligands have emerged as major determinants of tumor cell targeting by γδ T cells: ULBP4 in ovarian and colon carcinomas; and ULBP3 in B-cell chronic lymphocytic leukemia (CLL)." (PMID 29740448, 2018).
lung carcinoma (3 papers, 2014 to 2023). "The transcription of NKG2D ligands, namely, MHC class I polypeptide-related chain proteins A (MICA), MICB, UL16 binding protein 1 (ULBP1), ULBP2, and ULBP3, was analyzed after treating lung cancer cells with five types of HDAC inhibitor for 18 h." (PMID 34203519, 2021). "To investigate the relationship between the level of ULBP3 expression on tumor cells and the number of infiltrating NK cells in cancer tissues, we measured ULBP3 levels and the percentage of NK cells in tumor tissues from 10 cancer patients (4 colorectal cancer, 3 lung cancer, and 3 gastric cancer)." (PMID 25138242, 2014). "However, surface ULBP3 protein was undetectable on the lung cancer cell line A549 and esophageal carcinoma cell line ECA109." (PMID 25138242, 2014). "Treating NCI-H23 and A549 lung cancer cells with FK228 led to an increase in the transcription of the five NKG2D ligands: MICA, MICB, ULBP1, ULBP2, and ULBP3." (PMID 34203519, 2021). "In cancer patients with colorectal cancer (n = 5), liver cancer (n = 3), lung cancer (n = 3), and gastric cancer (n = 7), FCS indicated that ULBP3 expression was much higher in the tumor tissue than in the adjacent non-tumor tissue (ANTT)." (PMID 25138242, 2014).
melanoma (3 papers, 2011 to 2025). A malignant, usually aggressive tumor composed of atypical, neoplastic melanocytes. "For Ulbp3, on the other hand, no changes between the conditions were observed in both melanoma cell lines." (PMID 41078003, 2025).
acute myeloid leukemia (2 papers, 2022 to 2024). Acute myeloid leukemia (AML) is a group of neoplasms arising from precursor cells committed to the myeloid cell-line differentiation. "Sodium valproate, a low affinity pan HDACi, can induce the expression of NKG2D ligands MICA, ULBP2, and ULBP3 in tumor cells, including primary patient acute myeloid leukemia (AML) cells, resulting in enhanced CD107a degranulation of NK cells." (PMID 38665224, 2024).
COVID-19 (2 papers, 2024 to 2025). A disease caused by infection with severe acute respiratory syndrome coronavirus 2. "Soluble forms of other NKG2D-related ligands, ULBP2 and ULBP3, were also found to be significantly increased among COVID-19 patients suffering from severe infection, and their levels correlated with decreased expression of NKG2D." (PMID 41153412, 2025). "These analyses revealed that SARS-CoV-2 infection was associated with significant increases in levels of mRNA for the NKG2D ligands, ULBP2 and ULBP3 in COVID-19 patients with severe disease." (PMID 38410511, 2024).
glioblastoma (2 papers, 2019 to 2024). The most malignant astrocytic tumor (WHO grade IV). "Cell surface expression of the main ligands for the NKG2D receptor (MICA, MICB, ULBP1, ULBP2, and ULBP3) on the glioblastoma cell lines, U-251MG, T98G, and U-87MG, was assessed by flow cytometry." (PMID 31288857, 2019). "Three representative glioblastoma cell lines (U251, U87, A172) were selected for assessing cell surface expression of NKG2DL (MICA/B, ULBP1, ULBP2/5/6, ULBP3, and ULBP4) by flow cytometry." (PMID 39877353, 2024). "Next, the co-expression of the glioblastoma stem cell marker NESTIN and NKG2DLs (MICA, MICB, ULBP1, ULBP2, ULBP3) in these suspended cell spheres was assessed by flow cytometry." (PMID 31288857, 2019).
astrocytoma (1 paper, 2011). "Constitutive levels of NKG2D ligands are low in most cells, thus, to examine the effect of U21 upon the surface expression of the NK ligands, we generated U373 astrocytoma cell lines individually stably expressing ULBP1, ULBP2, ULBP3, MICA, or MICB, using retrovirus-mediated gene transfer." (PMID 22102813, 2011).
breast tumor (1 paper, 2012). "Most of the NKG2D ligands examined in this study were frequently expressed among the breast tumor cohort: MIC-AB in 50% of the cases; ULBP-1 in 90%; ULBP-2 in 99%; ULBP-3 in 100%; ULBP-4 in 26%; and ULBP-5 in 90%." (PMID 22257486, 2012).
cervical cancer (1 paper, 2014). A primary or metastatic malignant neoplasm involving the cervix. "More specifically, MICA/B, ULBP1 and RAET1E expression was significantly increased in cervical cancer tissues, while ULBP2 and ULBP3 expression were higher in low-grade CIN tissues, but lower in high-grade CIN and cervical cancer tissues." (PMID 25510288, 2014). "We then performed IHC analysis of MICA/MICB, ULBP1, ULBP2, ULBP3, RAET1E, and RAET1G in 200 cervical cancer specimens, 327 high-grade CINs, 99 low-grade CINs, and 541 matched nonadjacent normal cervical epithelial tissue samples." (PMID 25510288, 2014). "ULBP2 and ULBP3 expression, on the other hand, was higher in low-grade CIN than in normal epithelium but gradually decreased in high-grade CIN and cervical cancer (p = 0.001 and p = 0.017, respectively)." (PMID 25510288, 2014).
clear cell renal cell carcinoma (1 paper, 2023). "In clear cell renal cell carcinoma, MICA and ULBP3/RAET1N were both linked to poorer prognosis, while ULBP4/RAET1E was linked to improved outcomes." (PMID 37626965, 2023).
colon adenocarcinoma (1 paper, 2022). "A report showed that RAET1L together with ULBP1, ULBP2, ULBP3 had the high diagnostic values in colon adenocarcinoma (COAD)." (PMID 36294477, 2022).
colorectal cancer (1 paper, 2014). A primary or metastatic malignant neoplasm that affects the colon or rectum. "The colorectal cancer cell line CD133−SW620 expressed high levels (>50%) of ULBP3 (59.0 ± 2.6%, n = 3), and CD133+SW620 cells expressed moderate levels (20%–50%) of ULBP3 (22.0 ± 1.4%, n = 3)." (PMID 25138242, 2014).
laryngeal carcinoma (1 paper, 2023). Carcinoma that arises from the laryngeal epithelium. "In HNSCC, including tonsil and laryngeal cancers, ULBP2 had the highest expression level, ULBP1 had the highest, lowest, and ULBP3 was in between." (PMID 37565867, 2023).
liver cancer (1 paper, 2014). An epithelial or non-epithelial malignant neoplasm that arises from the liver. "The liver cancer cell line 7721 also expressed a moderate level of ULBP3 protein (30.0 ± 3.7%, n = 3)." (PMID 25138242, 2014).
malignant glioma (1 paper, 2014). A grade III or grade IV glioma arising from the central nervous system. "Additionally, transforming growth factor-beta (TGF-beta) selectively downregulates the expression of MICA, ULBP2, and ULBP4, but not MICB, ULBP1, or ULBP3, in malignant glioma cells." (PMID 24885711, 2014).
metastasis (1 paper, 2022). The spread or migration of cancer cells from one part of the body (where they first appeared) to another. "Non-responding patients had significant-downregulation of ULBP3 (p=0.0317) in patient without brain-metastasis and significant-upregulation/downregulation of PD-L1 and ULBP3 (p=0.0262/0.0286) in patients with pulmonary-metastasis." (PMID 36741391, 2022).
myeloma (1 paper, 2021). "We conclude that ULBP3 may either be playing a more important role in promoting NK cell attack in early-stage ND patients or that ULBP3 may be shed from the surface of myeloma cells in later-stage disease." (PMID 33435153, 2021). "In addition, when focusing only on ND patients, the expression of the NKG2D ligand, ULBP3, on BM myeloma cells negatively correlated with the expression level of NKG2D on both CD56bright and CD56dim NK cells in BM." (PMID 33435153, 2021).
osteosarcoma (1 paper, 2021). A usually aggressive malignant bone-forming mesenchymal neoplasm, predominantly affecting adolescents and young adults. "Interestingly, some NKG2D ligands (MICA, MICB, ULBP-2 and ULBP-3) are secreted from NSCLC, osteosarcomas and gastric cancer cells and may be shed by MMP-mediated cleavage." (PMID 34638439, 2021).
pancreatic cancer (1 paper, 2023). "In this study, gemcitabine upregulated the expression of MICB, ULBP1, ULBP2/5/6, ULBP3, and PVR in pancreatic cancer cell lines." (PMID 37169953, 2023).
reovirus infection (1 paper, 2023). "Thus, we further tested whether the intracellular protein levels of MICA, MICB, ULBP2, and ULBP3 were altered upon reovirus infection." (PMID 37753084, 2023). "Downregulation of the surface expression of MICA, ULBP2, and ULBP3 was observed in both MNT-1 and U87-MG cells following reovirus infection." (PMID 37753084, 2023). "To uncover the mechanism by which reovirus infection leads to the reduced expression of MICA, MICB, ULBP2, and ULBP3 in infected cells, we first evaluated their shedding from the cell surface." (PMID 37753084, 2023).
sarcoma (1 paper, 2020). A usually aggressive malignant neoplasm of the soft tissue or bone. "We observed that the high expression of DNAM-1 ligand CD155 as well as the high expression of NKG2D ligands ULBP1, ULBP2, and ULBP3 are negatively associated with survival in sarcoma patients." (PMID 32082316, 2020).
viral infections (1 paper, 2021). "Genes involved in defense response to bacterial or viral infections such as BPIFA2, CD48, ULBP3, NKG2D ligand 1-like, and NKG2D ligand 4-like were reported to have more copies in the genomes of Nubian ibex relative to the domestic goat reference." (PMID 34142199, 2021). "ULBP3 and NKG2D ligand 4-like expressions are induced by stressors, such as viral infections, heat shock, tissue damage, tumorigenesis, and DNA damage." (PMID 34142199, 2021).
tumor (27 papers, 2012 to 2025). "Low expression of ULBP3 was associated with high serum HBsAg level (p = 0.022) and tumor size (p < 0.001)." (PMID 36210637, 2023). "We found the mRNA expression level of MICA, MICB, ULBP1, ULBP2, ULBP4, and ULBP5 was significantly higher in tumor tissues than that in adjacent normal tissues, whereas ULBP3 expression was lower in tumor tissues compared to adjacent normal tissues." (PMID 36210637, 2023). "First, we observed that MICA and ULBP5 were significantly higher in HCC tumor tissues than those in paired normal tissues, while ULBP3 was lower in tumor tissues compared to normal tissues in the OEP000321 dataset and Guilin cohort." (PMID 36210637, 2023). "Our findings showed that dramatic downregulation of exosomal PD-L1, E-cadherin, ULBP1, ULBP3, MICA, MICB, Siglec7 and significant upregulation of exosomal PD-1 and IFN-gamma were associated with tumor regression." (PMID 36741391, 2022). "The effects of surface and soluble forms of ULBP3 on the interaction between tumor cells and NK cells were examined." (PMID 25138242, 2014). "In the present study, we demonstrated that ULBP3, like other NKG2DLs, was widely expressed on primary tumor cells and tumor cell lines." (PMID 25138242, 2014). "ULBP3 was expressed exclusively in the nucleus in both tumor and normal epithelial cells, while the other markers were expressed primarily in the cytoplasm, with some cases also demonstrating weak nucleus staining." (PMID 25510288, 2014). "In the present study, ULBP3 expression in several tumor cell lines and tumor tissue cells from common cancer types was analyzed." (PMID 25138242, 2014). "The results of RT-PCR analysis demonstrated that the ULBP3 gene was expressed in ULBP3-expressing tumor cell lines and in fresh tumor tissues from cancer patients, but not in ANTT." (PMID 25138242, 2014). "Our results demonstrate that tumor cells express surface and soluble ULBP3, which regulate NK cell activity." (PMID 25138242, 2014). "Given its lower expression in tumor tissues than in adjacent normal tissues, strategies aimed at upregulating ULBP3 could be explored as a therapeutic approach to enhance the immune recognition and destruction of tumor cells." (PMID 39866909, 2024). "Moreover, the expression of ULBP3 in HCC tumor tissues was much lower than that in adjacent tissues, and patients with low ULBP3 had a high level of serum HBsAg and poor RFS." (PMID 36210637, 2023). "Elevated expression of ULBP3 was identified in a large amount of tumor cell lines and tumor tissues, it regulated the activity of NK cells against tumors and could be a prominent target for immunotherapy." (PMID 35236310, 2022). "In addition, the ligands for activating NK cells, ULBP1 and ULBP3, which play an importing role in the NK-mediated immune response to tumor regression, were also upregulated in the arginine-free diet treated tumors." (PMID 34158865, 2021). "The NK cell cytotoxicity elicited by surface ULBP3-expressing tumor cells was stronger than that elicited by non-expressing tumor cells, suggesting that the expression of surface ULBP3 on tumor cells is directly related to the activity of NK cells against tumor cells." (PMID 25138242, 2014). "Importantly, high expression of ULBP3 on the cell surface of tumor cells augmented NKG2D-mediated NK cell cytotoxicity." (PMID 25138242, 2014). "We then examined the expression of ULBP3 in different tumor tissues." (PMID 25138242, 2014). "Given that tumor cells generally express surface ULBP3 and sULBP3, we investigated whether an anti-ULBP3 antibody altered the cytotoxic activity of NK cells against ULBP3-expressing tumor cells." (PMID 25138242, 2014). "Surface-expressed and soluble ULBP3 may have additive/synergistic effects and cooperate to reduce NK cell reactivity, thus enabling human tumor cells to evade NK-mediated surveillance." (PMID 25138242, 2014).